PCDH9 (protocadherin 9)
Diseases named in the same sentence as PCDH9 in open-access papers (continued):
Sharing a sentence is not in itself a finding about the gene and the disease.
tumor (continued). "Loss of PCDH9 reinforced tumor formation, and the treatment of β-elemene has no significant inhibition on tumor formation, while the transplantation of QBC-939 control cells formed a smaller tumor once upon treatment with β-elemene." (PMID 35903688, 2022). "This phenomenon is similar to the correlation between PCDH9 and other tumor cells (HCC)." (PMID 36387162, 2022). "This study identified PCDH9 as a potential tumor suppressor gene in MM." (PMID 36387162, 2022). "Survival analysis in the current study further proves the tumor suppressor function of PCDH9." (PMID 35840618, 2022). "Furthermore, PCDH9 was shown to act as a tumor suppressor by eliciting apoptosis and G0/G1 cell cycle arrest in glioma cells." (PMID 32694982, 2020). "Furthermore, tumor infiltration was mediated by tumor-derived EV-miR-1260b, which decreased PCDH9 expression in peri-tumoral NFs cells." (PMID 32523124, 2020). "PCDH9 has been reported to be a candidate tumour suppressor gene." (PMID 29649113, 2018). "In result downregulation of PCDH9 observed in our cell lines can lead to higher kinases activity, resulting in higher signal transduction, higher drug resistance and cell cycle genes expression leading to increased cells proliferation and tumor progression." (PMID 29649113, 2018). "However, expression of another candidate tumor suppressor, PCDH9, was remarkably decreased in HC cells when PKM2 activity was blocked, suggesting an alternative mechanism in PKM2-knockdown-resistant cells." (PMID 26576639, 2015). "Therefore, animal experiments presented that PCDH9 could work as a tumor suppressor gene to inhibit the growth of MM." (PMID 36387162, 2022). "In addition, studies found that the overexpression of PCDH9 could suppress different cancers and tumor cells by arresting cell cycle at G0/G1 phase." (PMID 36452505, 2022). "However, there are many reports describing PCDH9 as a tumour suppressor gene in many cancers." (PMID 29649113, 2018). "The role of PCDHs in this group of neoplasms has been evaluated in fifteen studies, and the most re-searched are PCDH7, PCDH8, PCDH9, and PCH10." (PMID 33369468, 2020). "The extracellular miR-1260b was embedded in tumor-derived extracellular vesicles (EVs) and promoted cellular invasion of MFS through the downregulation of PCDH9 in the adjacent normal fibroblasts." (PMID 32523124, 2020). "In oncogenesis, most Pcdhs seem to have a tumor suppressor function, as for several cancer types their downregulation [with the exception of PCDHB9, and PCDH9] correlates with tumor survival." (PMID 32694982, 2020). "We observed that when we subjected these mice to β-elemene treatment, the tumor derived from QBC-939 control cells almost stopped growing, while the tumor without PCDH9 continued to grow." (PMID 35903688, 2022). "In addition, according to a study, PCDHs located on chromosome 13q21, such as PCDH8, PCDH9, PCDH17, and PCDH20, may be involved in tumor suppression." (PMID 33369468, 2020).
cancer (10 papers, 2017 to 2026). A tumor composed of atypical neoplastic, often pleomorphic cells that invade other tissues. "All these results indicate that decreased/loss of PCDH9 expression correlates with different features of cancer disease progression." (PMID 29649113, 2018). "Restoring PCDH9 expression by β-elemene treatment is a major reason for the use of β-elemene in cancer therapy and interruption." (PMID 35903688, 2022). "The downregulation of PCDH9 has been shown to contribute to the development of various human cancers." (PMID 28427185, 2017). "Our results agreed with recent studies that found lower PCDH9 expression in various cancer types." (PMID 36452505, 2022). "Recent studies have found low PCDH9 expression in various cancer types." (PMID 36387162, 2022). "At the gene level, FDCSP (cancer cell migration and invasion), KIR2DL3 (immune response), SLC30A10 (antiapoptotic), MAB21L2, PCDH9 (cell adhesion), PEG3 (cell proliferation) were found to be highly expressed in the Lymph-node (LN)-positive samples." (PMID 37377901, 2023). "Consistent with results obtained from the TCGA-COAD cohort, six CRGs, including DPP7, GPRASP1, UNC5C, RAB3B, PCDH9, SLC18A2, were significantly downregulated, whereas CDR2L was upregulated in cancer tissues in comparison with paracancerous normal tissues." (PMID 37384293, 2023). "In addition, PCDH9 might be a drug target for cancer treatment." (PMID 28055966, 2017).
neurodevelopmental disorder (3 papers, 2020 to 2024). A behavioral and cognitive disorder with onset during the developmental period that involves impaired or aberrant development of intellectual, motor, or social functions. "Interestingly, PCDH9 has recently been identified as a risk gene for depressive disorder, often occurring in individuals with neurodevelopmental disorders." (PMID 33352832, 2020). "Studies on PCDH9 KO mice give insight in the possible roles of this protein in neurodevelopmental disorders including ASD." (PMID 33352832, 2020).
infection (1 paper, 2017). The state of being infected such as from the introduction of a foreign agent such as serum, vaccine, antigenic substance or organism. "In addition to the non-clustered PCDH8 and PCDH9 genes, several clustered PCDH genes were upregulated after 16 h of infection." (PMID 28993767, 2017).
PCDH9 also shares sentences with these, for which no sentence is quoted: depression (2 papers); nevus (2); brain cancer (1); cholangiocarcinoma (1); esophageal cancer (1); esophageal squamous cell carcinoma (1); lung adenocarcinoma (1); mantle cell lymphoma (1); medulloblastoma (1); mental disorder (1); microcephaly (1); neurofibroma (1); neurological disease (1); Obesity (1); papillary renal cell carcinoma (1); post-traumatic stress disorder (1); schizophrenia (1); soft tissue tumor (1); Timothy syndrome (1); type 2 diabetes (1).